EZH2 (enhancer of zeste 2 polycomb repressive complex 2 subunit)
Diseases named in the same sentence as EZH2 in open-access papers (continued):
Sharing a sentence is not in itself a finding about the gene and the disease.
breast cancer (continued). "Consistent with our observations in human breast cancers, IHC staining of EZH2, USP22, β2M, and CD8+ in serial tissue sections in human prostate and colon cancer tissue microarrays confirmed the increased expression of USP22 and EZH2 in tumors compared with benign tissues." (PMID 41252204, 2025). "EZH2 is highly correlated with breast cancer cell proliferation." (PMID 41413688, 2025). "In breast cancer, EZH2 and DNMT1 act synergistically to regulate CCL2 expression." (PMID 41341593, 2025). "For example, EZH2 expression is higher in breast cancer lymph node metastases compared to primary tumor tissues, suggesting that it may be a downstream epigenetic event of E2F activation." (PMID 40042761, 2025). "that Sox4 regulates EMT via the epigenetic modifier Ezh2, promoting breast cancer." (PMID 40978031, 2025). "Combination therapy consisting of EZH2 inhibitors and cisplatin could potentially be beneficial for the treatment of lung, ovarian, and breast cancer." (PMID 38791289, 2024). "In this study, we further examined the clinical significance of a four-gene signature (comprising CDK1, PCNA, EZH2, and BUB1) that may be associated with relapse events in untreated luminal breast cancer patients." (PMID 38831458, 2024). "The activation of STAT3 by EZH2 methylation has also been observed in the context of breast cancer." (PMID 39769907, 2024). "Therefore, the HIF-1/EZH2 signaling can be sustained inside extremely aggressive breast cancer cells devoid of the estrogen receptor (ER−), leading to the proliferation, invasion, migration, and angiogenesis of breast cancer cells." (PMID 38911968, 2024). "Finally, PRMT1 can mediate the asymmetric di-methylation of EZH2 at R342, which increases its stability and promotes breast cancer metastasis." (PMID 39769907, 2024). "EZH2 assumes an oncogenic role in a range of cancers, including solid tumors like breast cancer, prostate cancer, esophageal cancer, gastric cancer, anaplastic thyroid carcinoma, and endometrial carcinoma as well as in hematologic malignancies including follicular lymphoma." (PMID 39565059, 2024). "In addition, EZH2 inhibition reduced tumor burden and slowed progression in breast cancer both in vivo and in vitro." (PMID 38333212, 2024). "Interestingly, O‐GlcNAc has been shown to regulate EZH2 protein stability and function in breast cancer cells, which controls some tumour suppressor genes expression." (PMID 38494860, 2024). "Indeed, pharmacological inhibition of EZH2 has been shown to reduce breast cancer metastasis and enhance the efficacy of chemotherapeutics." (PMID 39409910, 2024). "To examine whether EZH2 represses mesenchymal genes in breast cancer cells in vivo, we used genome-wide gene expression datasets of 1904 resected breast cancer tumours available at the Molecular Taxonomy of Breast Cancer International Consortium." (PMID 39174513, 2024). "In addition, downregulation of the histone methyltransferases EZH2 and SUV39H1, observed after exposure to the combination of SFN, GE, and BS, is associated with reduced susceptibility to breast cancer." (PMID 38929688, 2024). "Moreover, YAP represses GDF15 transcription to promote metastasis of breast cancer cells by recruiting EZH2 and trimethylating histone H3 lysine 27 on the promoter of GDF15." (PMID 38245781, 2024). "Similarly, IFN-I expression was found to be silenced by H3K27me3 in breast cancer, while inhibition of EZH2 promoted STAT2-activated IFN signaling and MHC I expression." (PMID 39080807, 2024). "Therefore, we settled that EZH2 is required to downmodulate the expression of mesenchymal genes during EMT–MET in breast cancer cells and to allow efficient restoration of the epithelial state during MET." (PMID 39174513, 2024). "Thus, we concluded that EZH2 targets and represses the transcription of a large set of bivalent mesenchymal genes in the breast cancer cell line MCF-7." (PMID 39174513, 2024).
breast cancer (continued). "Since the discovery of Praja ring finger protein 1 (Praja1) in 2011, an E3 ubiquitin ligase that directly ubiquitinates EZH2 to reduce its protein levels and inhibit breast cancer progression, several other E3 ubiquitin ligases have been identified to regulate EZH2 protein stability in tumor cells." (PMID 39043634, 2024). "In breast cancer, EZH2 is reported to activate AKT isoform 1 and thus activate PI3K/AKT pathway." (PMID 39072246, 2024). "Consequently, elevated EZH2 levels promote metastasis of breast cancer cells by suppressing the expression of target genes such as E-cadherin, DAB2IP, and CSTA." (PMID 38326807, 2024). "Kaplan-Meier survival analysis using The Cancer Genome Atlas (TCGA) dataset also revealed both EZH2 and integrin α11 could be strong prognostic factors of relapse-free and overall survival in breast cancer patients." (PMID 38664825, 2024). "To examine whether EZH2 regulates transitions between the epithelial and mesenchymal states of breast cancer cells we setup an in vitro system to study the dynamics of EMT and its reverse process (mesenchymal to epithelial transition, MET)." (PMID 39174513, 2024). "Therefore, these analyses support that EZH2 functions as a transcriptional repressor of the mesenchymal gene expression programme in human breast cancer tumours." (PMID 39174513, 2024). "In addition, SND1, a known pro-oncogenic protein, augments the binding of HIF-1α to EZH2, contributing to the development of breast cancer induced by the polyomavirus middle T antigen (PyMT)." (PMID 38911968, 2024). "Here, we asked whether direct transcriptional regulation of mesenchymal genes by EZH2 also occurs in breast carcinoma cells." (PMID 39174513, 2024). "miR-92b can perform multiple functions by regulating multiple target mRNAs, such as suppressing viability and invasion by targeting EZH2 in breast cancer, and attenuate inflammation by affecting the expression of TRAF3 and inhibiting the MKK3-p38 pathway in acute pancreatitis." (PMID 36670839, 2023). "The content of EZH2 was found to be elevated in breast cancer SCs in comparison with normal tissue-specific SCs, suggesting that EZH2 may initiate cancer growth by blocking the differentiation of somatic SCs." (PMID 36769153, 2023). "EZH2 can also methylate STAT3 in breast cancer cells, which was necessary for tumor growth." (PMID 37664059, 2023). "Studies have shown that simultaneous induction of miR-101 and treatment with Syn-cal14.1a, a synthetic peptide acquired from Californiconus californicus, suppresses EZH2-induced breast cancer cell migration, invasion, and proliferation and promotes apoptosis of BC cells." (PMID 38132441, 2023). "Indeed, many preclinical studies have demonstrated the efficacy of EZH2 inhibition in combination with cisplatin in different tumor types, such as lung, ovarian, and breast cancers." (PMID 36900330, 2023). "Moreover, a recent study has revealed the cooperation between EZH2 and TGFβ signaling in promoting bone metastasis of breast cancer also through a methyltransferase-independent manner." (PMID 37369946, 2023). "Notably, highly expressed phosphorylated EZH2 is differently located in cytoplasm or nucleus in a site-specific manner in breast cancer cells." (PMID 37803297, 2023). "Similarly, another study illustrated that methylation of EZH2 by PRMT1 at R342 promoted breast cancer cell EMT, invasion, and metastasis, and high levels of EZH2 methylation was associated with poor clinical outcome in breast cancer patients." (PMID 37737256, 2023). "MS1943, an EZH2 selective degrader, effectively reduces EZH2 levels in breast cancer." (PMID 37760442, 2023). "EZH2 could induce the oncogenic transformation of mammary epithelial cells and serve as a key biomarker of aggressive breast cancer." (PMID 36545914, 2023). "EZH2 R342 methylation by PRMT1 increases EMT of breast cancer cells." (PMID 37143582, 2023). "Functional interaction of EZH2 with ERRs was evidenced in gastric and breast cancers." (PMID 36901694, 2023).
breast cancer (continued). "Accordingly, we speculated that EZH2 might cooperate with PAX2 in breast cancer, which needs to be further investigated." (PMID 36318256, 2023). "When the EGR1 signal was dampened in breast cancer by EZH2, cell growth, migration, and invasion, and tumorigenesis of breast cancer cells could be recovered or strengthened." (PMID 37188478, 2023). "In addition, cell cycle protein-dependent kinase 1 (CDK1)-mediated phosphorylation of threonines 345 and 487 promotes ubiquitinated degradation of EZH2 in breast cancer cells, cervical cancer cells, and LC cells." (PMID 37909018, 2023). "Related to metastasis, for instance, EZH2-dependent methylation of p38α enhances its stability and function; and the cooperation between EZH2 lysine methyltransferase and p38 kinase activities promotes breast cancer growth and metastasis." (PMID 37369946, 2023). "EZH2 has been reported as a transcriptional activator of ESR1 expression in breast cancer cells." (PMID 35326450, 2022). "Further analysis revealed that VEGFA and EZH2 were negatively correlated with their respective upstream miRNAs in breast cancer and were significantly overexpressed in breast cancer compared with normal breast controls and indicated poor prognosis of patients with breast cancer." (PMID 35812757, 2022). "The underlying mechanism of increased cytotoxicity by combined EZH2/ATM inhibition in BRCA1-deficient breast cancer cells is not clear." (PMID 35715861, 2022). "We found that combination therapy of EZH2 inhibitors and cisplatin could potentially be beneficial for the treatment of lung, ovarian, and breast cancers." (PMID 36230683, 2022). "However, in breast cancer, estrogen response elements (EREs) have been reported in promoter sequences of EZH2; moreover, E2 directly regulates the expression of EZH2 through its nuclear receptors." (PMID 35197928, 2022). "EZH2 is positively correlated with LOXL4 expression and tumor-associated macrophage infiltration (TAM), and LOXL4 knockdown can inhibit the proliferation and metastasis of breast cancer cells." (PMID 36293126, 2022). "To validate the role of EZH2 as a therapeutic target and to identify new synergistic drug combinations, we performed a high-throughput drug combination screen in various cell lines derived from BRCA1-deficient and -proficient mouse mammary tumors." (PMID 35715861, 2022). "It has been previously reported that CDK1 promotes the migration and metastasis of cancer cells, e.g., colorectal carcinoma and breast cancer cells, by phosphorylating proteins such as EZH2 and activating pathways such as the Wnt/β-Catenin and ERK/GSK3β/SNAI axes." (PMID 35806389, 2022). "According to the data presented, the use of cisplatin and EZH2 inhibitors may be beneficial in the treatment of lung, ovarian, and breast cancers, since there is a substantial amount of published evidence that suggests their concerted action." (PMID 36230683, 2022). "Breast cancer cells can be resensitized to taxane upon EZH2 inhibition." (PMID 35203421, 2022). "We show that the combined treatment with the EZH2 inhibitor GSK126 and the ATM inhibitor AZD1390 led to reduced colony formation, increased genotoxic stress, and apoptosis-mediated cell death in BRCA1-deficient mammary tumor cells in vitro." (PMID 35715861, 2022). "In addition, EZH2 regulates the NF-κB pathway by interacting with RelA and RelB complexes to regulate the development of breast cancer." (PMID 35813295, 2022). "Here we found that depletion of EZH2 blocked breast cancer bone metastasis in vivo." (PMID 35538070, 2022). "As alterations in EZH2 expression alone are insufficient for breast cancer development, additional factors along with estrogen-induced EZH2 overexpression are necessary for ER+ breast cancer development." (PMID 35453496, 2022). "We provide a rationalized approach of a synergistic therapy with EZH2 and ATM inhibition in BRCA1-deficient breast cancer that could guide further preclinical and clinical investigations." (PMID 35715861, 2022).
breast cancer (continued). "Conclusively, VEGFA and EZH2 may be the most potential targets in the DNMT3B-related miRNA–mRNA network in breast cancer." (PMID 35812757, 2022). "And till now, the precise mechanism by which EZH2 affects TAMs polarization and breast cancer progression remains unclear." (PMID 36038549, 2022). "EZH2, namely, the enzymatic subunit of polycomb repressive complex 2, has been found to be of great importance in various cancers, including bladder cancer, breast cancer, prostate cancer, and so on." (PMID 34420511, 2022). "However, the expression of EZH2 in breast cancer is highly correlated with tumorigenesis, and patient survival is not matched to TNBC." (PMID 35813302, 2022). "Consequently, EZH2 functions in breast cancer as a double-sided molecule that, acts as a transcriptional activator or repressor of NF-κB targets depending on the cellular context." (PMID 36313363, 2022). "Moreover, EZH2 showed an oncogenic role in promoting tumoral growth and cell invasion in breast cancer by the inhibition of E2F1-dependent apoptosis pathway by the epigenetic modulation of BIM expression." (PMID 36135315, 2022). "Pathway enrichment analysis revealed that the target genes of these miRNAs were markedly enriched in some cancer-related pathways, and further investigation indicated VEGFA and EZH2 were found to be the most potential target genes in the m5C regulators-related ncRNA–mRNA network in breast cancer." (PMID 35812757, 2022). "The EZH2 enrichment subsequently enhanced breast cancer metastasis." (PMID 35805995, 2022). "Indeed, it has been shown that in prostate cancer, breast cancer and in leukemia, EZH2 is also recruited to oncogenes to promote gene activation independently of its enzymatic activity." (PMID 36105358, 2022). "As described herein, we revealed a mechanism of how EZH2 promotes breast cancer bone metastasis." (PMID 35538070, 2022). "To draw a clinical correlation between EZH2 and KRT14 expression, we mined Breast Cancer Yau (2010) dataset from breast cancer patients and observed a high EZH2 and KRT14 mRNA expression exclusively in the basal (TNBC) subtype compared to the other breast cancer subtypes." (PMID 36446780, 2022). "What’s more, EZH2 interacts directly with estrogen receptor and β-catenin through transactivation in its two N-terminal domains, thereby linking estrogen and Wnt signaling pathways to promote cell cycle progression and ER-positive breast cancer progression." (PMID 36313363, 2022). "Further, we attempted to figure out the specific regulatory mechanism, which might be one of the reasons for limiting the benefits of EZH2 inhibitors against breast cancer." (PMID 36038549, 2022). "Targeting the EZH2–CCF–cGAS axis may be a potential therapeutic strategy for inhibiting breast cancer metastasis." (PMID 35163710, 2022). "Although GBMs and breast cancer are estrogen-responsive tumors, they have different biological contexts in which the role of EZH2 and the mechanisms controlling its expression may be different, as has been suggested in neoplastic cells." (PMID 35197928, 2022). "Similarly, a previous study showed that inhibiting PARylation of EZH2 promotes the EZH2-mediated epigenetic gene silencing and regulates tumor response to PARPi in BRCA-mutated breast cancer." (PMID 36284291, 2022). "However, we primarily observe peritoneal and lung metastasis but not brain metastases in our in vivo imaging experiments following orthotopic inoculation of EZH2 hyperactive breast cancer cells." (PMID 36446780, 2022). "Moreover, EZH2, a transcriptional repressor of several anti-proliferative genes, has been shown to undergo methylation by SMYD2, leading to EZH2 stability and therefore enhancing cell proliferation in breast cancer." (PMID 35022391, 2022). "This section is dedicated to discussing miRNA and EZH2 interaction in breast cancer cells." (PMID 35236381, 2022). "It has been reported that miRNA/EZH2 axis can regulate the therapy response of breast cancer cells." (PMID 35236381, 2022).
breast cancer (continued). "Furthermore, EZH2 inhibition has been shown to sensitise breast cancer cells to PARPi and PARPi can regulate EZH2 expression via PARPylation." (PMID 35326684, 2022). "Gene array studies revealed the minimal overlap of genes regulated by HOTAIR between PC and breast cancer cells, and further research using EZH2 knockdown and chromatin immunoprecipitation demonstrated that gene repression mediated by HOTAIR was both PRC2-dependent and PRC2-independent." (PMID 35565245, 2022). "EZH2 acts as an oncogene in various neoplasms such as breast cancer, prostate cancer, and GBMs." (PMID 35197928, 2022). "Interestingly, EZH2 acts inversely in ER-positive luminal breast cancer cells and suppresses the expression of NF-κB target genes by interacting with ER and directing repressive histone methylation to its promoters." (PMID 36313363, 2022). "Specifically, ANCR exerts anti-tumor activity in breast cancer via regulating EZH2 expression." (PMID 35236381, 2022). "To study whether EZH2 promotes breast cancer cell migration and invasion through cGAS, we treated MM-231 cells with EPZ-6438 and observed that EPZ-6438 impaired cell migration and invasion." (PMID 35163710, 2022). "Moreover, EZH2 overexpression identifies patients with breast cancer who benefit from a high-dose DSB-inducing platinum-based chemotherapy." (PMID 36230683, 2022). "Among this PPI network, PTEN, CCND1, VEGFA, CDC42, and EZH2 were ranked as the top five hub genes, which may function as key genes in the m5C regulators-related miRNA–mRNA regulatory network in breast cancer." (PMID 35812757, 2022). "However, targeting EZH2 downstream effector FAK with clinically applicable kinase inhibitors have striking effects on blocking breast cancer bone metastasis." (PMID 35538070, 2022). "Interestingly, another hub gene, COL5A1, as a target of EZH2, is upregulated by decreased activity of EZH2 in the breast carcinoma cell line." (PMID 35571032, 2022). "Moreover, hyperactivation and overexpression of EZH2 has been found in diverse malignant tumors including prostate, uterine, gastric, breast cancers, and lymphoma." (PMID 34577136, 2021). "Besides, metformin treatment in breast cancer can increase mir-26a levels, inducing cell cycle arrest, and apoptosis through EZH2 regulation." (PMID 34123772, 2021). "In addition, we found that miR-378 expression was positively correlated with β-catenin, NOTCH1 and EZH2 expression in breast cancer based on the TCGA database (n = 470) (p < 0.001)." (PMID 33823894, 2021). "Despite the key role of EZH2 in repressing Notch signaling in T-ALL, a positive correlation between EZH2 and Notch was found in glioblastoma and breast cancer in which EZH2 directly binds Notch1 promoter, upregulating Notch1 expression without any change in H3K27me3 levels." (PMID 34680255, 2021). "Therefore, STAT3 methylation by EZH2 was critical for the nuclear localization in breast cancer cells." (PMID 34335938, 2021). "Furthermore, we show that EZH2 protein levels are increased in breast cancer cell lines compared to normal breast epithelial cells." (PMID 33750924, 2021). "EZH2 promotes proliferation and migration of breast cancer cells by methylating STAT3." (PMID 34335938, 2021). "Taken together, our results suggest that NOTCH and EZH2, working together in a feed forward loop, could control tumorigenic phenotypes in a subset of breast cancer cases through repression of PTEN expression." (PMID 33750924, 2021). "This suggested that EZH2 is required for PRMT1 to facilitate breast cancer cell proliferation." (PMID 34775498, 2021). "A large body of studies have manifested that EZH2 plays the pivotal role in breast cancer 3,4." (PMID 34335938, 2021). "Furthermore, ANCR, the long non-coding RNA (lncRNA), can promote the CDK1–EZH2 interaction, resulting in EZH2 ubiquitination and its degradation in breast cancer cells in vitro." (PMID 34944867, 2021).